FSTL1 (follistatin like 1)
Diseases named in the same sentence as FSTL1 in open-access papers (continued):
Sharing a sentence is not in itself a finding about the gene and the disease.
tumor (continued). "According to classification as detailed described in method, overexpression of FSTL1 was detected in 96 out of 130 (73.8%) CRC cases compared with 34 out of 103 (33.0%) in adjacent non-tumour tissues." (PMID 29844309, 2018). "Taken together, the data on the expression levels of FSTL1 in relation with its effect in different tumours are highly variable from respect to growth inhibition or induction and from invasiveness to immobility." (PMID 29594389, 2018). "Further analysis showed that the tumour suppressor function of FSTL1 is mediated through repression of the NF-κB and HIF-2α signaling pathways." (PMID 29594389, 2018). "In vivo studies, further showed that injection of an FSTL1 siRNA into a subcutaneous tumour suppressed tumour growth and the formation of bone metastasis, increasing mouse survival compared to injections with a control siRNA." (PMID 29594389, 2018). "A total of 89 ccRCC patients who had IHC scores of FSTL1 expression in tumor tissues were successfully followed up after surgery." (PMID 29357946, 2018). "Similar in vivo results were observed in NSCLC; tumour growth was inhibited when FSTL1 was overexpressed in the CL1-5 cell line and promoted when FSTL1 expression was downregulated in the CL1-0 cell line." (PMID 29594389, 2018). "The effect of FSTL1 on tumour metastasis was assessed by spleen subcapsular injection of human CRC cells into nude mice." (PMID 29844309, 2018). "With respect to imbalanced tumour growth, contradictory results have also been reported upon in vitro manipulation of the level of expression of FSTL1 in cell lines." (PMID 29594389, 2018). "A significant increase of FSTL1 was seen in human CRC as compared to the surrounding non-tumor tissues and this occurred at both RNA and protein level." (PMID 30131854, 2018). "FSTL1 is up-regulated in a highly metastatic prostate cancer cell line and in most tumour tissue of glioblastoma multiforme patients." (PMID 29844309, 2018). "In contrast, FSTL1 exerts tumor-suppressive actions in ovarian and endometrial carcinogenesis and its expression is down-regulated in metastatic clear-cell renal-cell carcinoma." (PMID 30131854, 2018). "Subcutaneous tumorigenicity testing showed that knockdown of FSTL1 in CL1-0 cells promoted the tumor growth." (PMID 28852126, 2017). "We then sought to validate the role of FSTL1 as a tumor suppressor gene by in vitro and in vivo studies." (PMID 26918942, 2016). "FSTL1 was downregulated in the 25 NPC primary tumor samples but easily detected in all 8 normal nasopharyngeal epithelium (NNE) samples (P < 0.05)." (PMID 26918942, 2016). "A decreased expression of FSTL1 in a panel of human cancers suggest a tumor-suppressive function for it." (PMID 26918942, 2016). "IHC score of FSTL1 was significantly higher in adjacent normal renal tissues than in tumor tissues in the RCC patients with rs1259293 CT + CC genotypes." (PMID 27225192, 2016). "To assess the potential tumor suppressor properties of FSTL1, we established stable FSTL1-expressing CNE2 cells and examined their effect on cell colonogenicity, proliferation, migration, invasion and apoptosis." (PMID 26918942, 2016). "In RCC patients with rs1259293 TT genotype, IHC score of FSTL1 was significantly higher in adjacent normal renal tissues than in tumor tissues." (PMID 27225192, 2016). "In NPC cells, we found that ectopic expression of FSTL1 inhibited tumor cell migration and invasion." (PMID 26918942, 2016). "In ovarian and endometrial cancers, FSTL1 functions as a tumor suppressor through pro-apoptotic activities." (PMID 27225192, 2016). "Cancer metastasis is amplified by CCL2 and FSTL1, which are abundantly produced by both the sMSCs and the metastatic tumor cells within the tumor microenvironment." (PMID 25883937, 2015).
tumor (continued). "We found that the sMSCs prepared either in vitro or in vivo specifically produce ANGPT2, CCL2, CCL3, and FSTL1, and most powerfully affect tumor behavior and host immunity by using these molecules (unpublished data except CCL2)." (PMID 25883937, 2015). "Among the Snail+ tumor-producing factors, FSTL1, which is a member of the SPARC family, is an outstanding molecule playing a dual role in cancer metastasis particularly to the bones." (PMID 25883937, 2015). "FSTL1 confers the invasive potential and bone tropism on tumor cells, and also generates and expands CD45−ALCAM+ MSCs initially in bone marrow and sequentially all over the body in the host." (PMID 25883937, 2015). "This points to the in vivo existence of a causal molecular connection between FSTL1 and ALCAM within the tumor microenvironment in patients." (PMID 25883937, 2015). "We found FSTL1 is an oncogene in cSCC, with high expression in tumor tissues and cells." (PMID 38605354, 2024). "Mounting evidence indicates FSTL1 plays a key role in tumor formation." (PMID 38605354, 2024). "In summary, the results indicated that FSTL1 might play the role as a tumor suppressor, and its high expression in CC cells can inhibit cell growth in vitro." (PMID 36756161, 2023). "FSTL1 expression decreased in the CC tumor tissues compared with its matched adjacent tissues." (PMID 36756161, 2023). "Furthermore, TFE3, TFDP1, NFYB, and RB1, associated with the cell cycle and apoptosis, were inferred in FSTL1+ tumor cells." (PMID 37430270, 2023). "In summary, our study has demonstrated that FSTL1 has a tumor suppressor effect in CC." (PMID 36756161, 2023). "We found evidence to prove the tumor suppressor function of FSTL1 in cervical carcinogenesis." (PMID 36756161, 2023). "Immune cell infiltration in the TME is closely related to tumor prognosis, and FSTL1 may be able to evolve cancer immunotherapy to treat malignant tumors and their metastasis." (PMID 37238210, 2023). "Indeed, FSTL1 has been demonstrated to equip HCC cells with tumor-initiating and drug resistance abilities." (PMID 36708970, 2023). "The Follistatin-related protein 1 (FSTL1) primary mRNA transcript also encoded for miR-198, and the switch between expression of the FSTL1 protein and miR-198 is an important regulator of tumor metastasis and wound healing." (PMID 35563788, 2022). "Blocking FSTL1 could significantly inhibit tumor progression and metastasis in a mouse tumor model with increased MSCs." (PMID 35805015, 2022). "FSTL1 may play a pro-angiogenic role in tumor development and angiogenesis (survival and migration) in a manner similar to that shown in vitro and in ischemic tissues." (PMID 33714952, 2021). "Furthermore, the Fstl1+/- tumor-bearing mice also displayed a decrease in thymus size and thymocyte number compared to that in WT mice." (PMID 33639614, 2021). "Since the volume of the primary tumor was same in the WT and Fstl1+/- mice, the decreased number of infiltrated CD4+ T cells in the primary tumor may promote the escape of cancer cells and accelerate the metastasis of 4T1 cells." (PMID 33639614, 2021). "To date, the complexity and variety of mechanisms underlying tumor development do not allow us to form a complete picture of the role of FSTL1 in the development and progression of cancer." (PMID 34440203, 2021). "In this study, we explored immune microenvironment in the lungs of Fstl1+/- tumor-bearing mice." (PMID 33639614, 2021). "Aberrant expression of FSTL1 has been demonstrated in tumor cell lines and clinical tumor biopsy specimens, which implies that FSTL1 may play different roles in different types of cancers." (PMID 33639614, 2021). "Hence, FSTL1 plays a crucial role in immune cell infiltration and tumor-immune system interactions in GC." (PMID 33292276, 2020). "From these results, we can speculate that FSTL1 is crucially involved in tumor progression and tumor immunity." (PMID 33292276, 2020).
tumor (continued). "FSTL1 plays a crucial role in tumor-immune and cancer cell progression." (PMID 33292276, 2020). "Moreover, the results indicated that high expression level of FSTL1 was correlated with tumor size, lymph node metastasis, and TNM stage, especially." (PMID 33292276, 2020). "For these reasons, FSTL1 might be a promising prognostic biomarker for cancer and could provide new ideas for improving tumor immune evasion and immunotherapy in GC." (PMID 33292276, 2020). "Hence, FSTL1 is closely correlated with tumor-infiltrating immune cells and indicates that FSTL1 plays a vital role in the immune escape mechanism in patients with GC." (PMID 33292276, 2020). "Follistatin-like 1 (FSTL1) plays a central role in the progression of tumor and tumor immunity." (PMID 33292276, 2020). "During cancer bone metastasis, Fstl1 promotes tumor cells invasion and bone tropism." (PMID 30542120, 2019). "However, upregulation of Fstl1 induces apoptosis in ovarian and endometrial cancer cells to act as a tumor suppressor." (PMID 30542120, 2019). "FSTL1 expression was examined by using IHC in all 89 tumor tissues, and 67 adjacent renal tissues." (PMID 29357946, 2018). "Overexpression of FSTL1 in ESCC cells (KYSE-150) promoted tumour growth and metastasis in vivo." (PMID 29594389, 2018). "FSTL1 expression score was also higher in tumour tissues (P < 0.0001)." (PMID 29844309, 2018). "FSTL1 functions as a tumor suppressor possibly via repressing NF-κB and HIF-2α signaling pathways." (PMID 29357946, 2018). "In ovarian and endometrial cancers, FSTL1 functions as a tumor suppressor via inducing apoptosis." (PMID 29357946, 2018). "Moreover, both mRNA and protein levels of FSTL1 were downregulated in tumors as compared to non-tumor tissues from patients with LUAD." (PMID 28852126, 2017). "On the other hand, FSTL1 overexpression in CL1-5 cells inhibited the tumor growth." (PMID 28852126, 2017). "Expression of FSTL1 was significantly higher in adjacent normal renal tissues than in paired tumor tissues and significantly higher in the tumor or paired adjacent renal tissues of RCC patients with rs1259293 TT genotype than in those with rs1259293 CT + CC genotype." (PMID 27225192, 2016). "However, one report in 2013 showed that FSTL1 plays a dual role in cancer bone metastasis, firstly by mediating tumor invasion and bone tropism, and secondly, by expanding the population of pluripotent mesenchymal stem-like cells." (PMID 26918942, 2016). "We therefore hypothesized that inhibition of FSTL1 might contribute to the escape of NPC tumor cells from immune surveillance." (PMID 26918942, 2016). "Based on this straightforward mechanistic rationale and the results of our study, it is reasonable to speculate that FSTL1 is a tumor suppressor in RCC, and rs1259293 CC genotypes contribute to low FSTL1 expression, which therefore predicts a poor prognosis." (PMID 27225192, 2016). "The role of FSTL1 in tumor invasion and metastasis is complex." (PMID 26918942, 2016). "It was suggested involvement of Cx43 cellular factor to the FSTL1-mediated tumor suppression." (PMID 26918942, 2016). "Expression of FSTL1 was significantly higher in adjacent normal renal tissues than in paired tumor tissues and significantly higher in the tumor or paired adjacent renal tissues of RCC patients with rs1259293 TT genotype than in those with rs1259293 CT + CC genotypes at the protein level." (PMID 27225192, 2016). "Our data suggest the role of FSTL1 as a tumor suppressor gene in NPC." (PMID 26918942, 2016). "FSTL1 might exert pro-angiogenic effects (survival, migration) during development and tumor angiogenesis in a similar manner as has been shown in vitro and in ischemic tissue." (PMID 19924294, 2009).
tumor (continued). "Paraffin sections of mouse tumor tissues were subjected to immunohistochemistry, showing weakened Ki67 staining (indicating reduced proliferation), increased E-cadherin (indicating more epithelial properties), and reduced N-cadherin (indicating less mesenchymal properties) in sh-FSTL1 tumors." (PMID 38605354, 2024). "This indicates that FSTL1+ tumor cells may act as CSCs with high apoptosis potential." (PMID 37430270, 2023). "Furthermore, Th1 cells also reduced in the lung of Fstl1+/- tumor-bearing mice." (PMID 33639614, 2021). "It implied that endogenous FSTL1 may regulate the proliferation and metastasis of tumor cells." (PMID 33639614, 2021). "Thus, we further investigated the relationship between FSTL1 expression and tumor immunity." (PMID 33292276, 2020). "However, the tumour growth rate was lower in FSTL1-transfected NPC cells compared to control cells." (PMID 29594389, 2018). "Therefore, the exact function of FSTL1 in the tumour needs to be further investigated." (PMID 29844309, 2018). "While this study was ongoing, Gu and colleagues showed that FSTL1 expression is significantly up-regulated in CRC tissues compared with the paired normal tissues and the higher FSTL1 expression in CRC associated with the infiltrating depth, lymph node metastasis and poor prognosis of the neoplasia." (PMID 30131854, 2018). "However, FSTL1 was a small impact on tumor growth in our study." (PMID 25883937, 2015). "In contrast, COL3A1 and FSTL1 were significantly overexpressed in SKCM-P, pointing to a potential role in early-stage tumor development and offering targets for early detection and intervention." (PMID 40943183, 2025). "Several additional genes—including FSTL1, LRPAP1, MSX1, and APP—exhibited distinct immune interaction profiles, suggesting diverse roles in modulating tumor–immune dynamics." (PMID 40943183, 2025). "Our study first identified the pro-oncogenic role of FSTL1 in cSCC and revealed a novel mechanism, THOC7-AS1/OCT1/FSTL1, regulating EMT and promoting tumor progression, demonstrating significant innovation." (PMID 38605354, 2024). "Thirdly, we elucidated the molecular mechanism of FSTL1 regulation, demonstrating that the THOC7-AS1/OCT1/FSTL1 axis promotes epithelial-mesenchymal transition in cSCC cells, thus advancing tumor progression." (PMID 38605354, 2024). "Thus, we hypothesized that FSTL1 promotes tumor infiltration through EMT." (PMID 38605354, 2024). "On the other hand, pRCC showed upregulation of TFPI2, FSTL1, FAS, and PIGR in the epithelial/tumor, C1QTNF3 and GRN in the endothelial, and ITGAX, HLA-DQA1, IL4I1, and CTSC in the immune compartments." (PMID 38703764, 2024). "In conclusion, the THOC7-AS1 ASO effectively modulated the expression of FSTL1 and its downstream targets through the THOC7-AS1/OCT1/FSTL1 axis, leading to a significant inhibition of cSCC tumor growth." (PMID 38605354, 2024). "Lastly, cells from the combination therapy PD-1+SMI group were mainly clustered in the apoptotic branch (NNMT+ and FSTL1+ tumor cells), suggesting that PD-1 inhibitor combined with SMI induces tumor apoptosis." (PMID 37430270, 2023). "NNMT+ and FSTL1+ tumor cells displayed significantly higher pro-apoptosis scores than anti-apoptosis score, while other subcluster cells displayed significantly higher anti-apoptosis scores than pro-apoptosis scores, suggesting that NNMT+ and FSTL1+ tumor cells may be susceptible to apoptosis." (PMID 37430270, 2023). "The intersection set analysis of the bioinformatics database and transcriptome array data identified six common genes, FSTL1, GDF15, IQSEC2, KDM3A, LTC4S and TCTEX1D4, in which most of them were involved in tumor cell proliferation and growth." (PMID 38201443, 2023). "These genes were FSTL1, GDF15, IQSEC2, KDM3A, LTC4S and TCTEX1D4, in which most of them were involved in tumor cell proliferation and growth." (PMID 38201443, 2023).
tumor (continued). "In our research, the Fstl1+/- mice had the same volume of primary tumor as the WT mice; however, IHC staining showed that the number of infiltrated CD4+ T cells in the primary tumor was significantly decreased in Fstl1+/- mice compared to that in WT mice." (PMID 33639614, 2021). "Thus, FSTL1 might be a novel tumor suppressor that attenuates EMT process in ccRCC cells." (PMID 29357946, 2018). "In this study, we show that FSTL1 is constitutively expressed in the normal colon and its expression is enhanced in CRC samples relative to surrounding non-tumor tissues." (PMID 30131854, 2018). "FSTL1 was frequently downregulated in NPC cell lines and primary tumor biopsies by promoter hypermethylation." (PMID 26918942, 2016). "In this study, we identified decreased FSTL1 expression in NPC tissue sections, concomitant with downregulation of IL-1β and TNF-α in tumor tissue macrophages." (PMID 26918942, 2016). "In this study, we first investigated the expression and methylation status of FSTL1 in NPC cell lines and primary tumor tissues." (PMID 26918942, 2016). "FN1 functionally connects a pair of coexpressed glycoproteins, FBLN1 and FSTL1, and SPARC is connected to IGFBP7, a tumor suppressor, which creates a functional link between a candidate tumor suppressor, PDGFRL, and a mesenchymal factor, FSTL1." (PMID 24944582, 2014). "The THOC7-AS1/OCT1/FSTL1 axis regulates EMT and promotes tumor progression in cSCC." (PMID 38605354, 2024). "Among the 11 pairs of biopsies (patient No. 1-11) examined, the FSTL1 mRNA transcription level in each tumor was markedly lower than that in the matched adjacent tissue using qRT-PCR." (PMID 36756161, 2023). "By consulting the literature, we found that COL5A1 is related to immune infiltration in the tumor microenvironment (TME) of GC patients, so we wondered whether FSTL1 was also involved." (PMID 35805015, 2022). "MiR-137-3p played a tumor-suppressive role in GC, and its target gene COL5A1 could reversely sponge miR-137-3p to relieve its targeted inhibition of FSTL1, which might promote the progression of GC by affecting immune infiltration." (PMID 35805015, 2022). "Previous studies suggest that it plays a role in respiratory diseases, cardiovascular system, immune system, and tumor diseases, but research is lacking regarding FSTL1 in ophthalmology." (PMID 33714952, 2021). "Univariate analysis indicated that tumor size (P < 0.001), depth of invasion (P < 0.001), lymph node metastasis (P < 0.001), TNM stage (P < 0.001), vascular invasion (P = 0.003), and FSTL1 expression (P < 0.001) were significantly correlated with OS of GC patients." (PMID 33292276, 2020). "Injection of NPC cells stably transfected with FSTL1 in nude mice showed a similar tumour incidence compared to non-transfected cells." (PMID 29594389, 2018). "Most cell lines derived from human tumours express lower levels of FSTL1 than immortalized non-tumourigenic fibroblasts." (PMID 29594389, 2018). "In addition to the genes discussed, there were additional stromal genes identified by the NN analysis, including CDH11, OLML3, FSTL1, AEBP1, VCAN, previously reported to correlate with tumor progression and metastasis in various cancers." (PMID 27128408, 2016). "We compared the biological properties between Snail/FSTL1-expanded MSCs (designated “sMSCs”) and other MSCs manipulated by none or non-metastatic tumor cells prepared in vitro and in vivo." (PMID 25883937, 2015). "The expression of COL5A1 or FSTL1 was significantly positively correlated with the three types of scores, and the correlations between the expression of FSTL1 and those scores were significantly higher than that of COL5A1, suggesting that FSTL1 may affect tumor immune infiltration in GC patients." (PMID 35805015, 2022).